ATAD2 (ATPase family AAA domain containing 2)
Diseases named in the same sentence as ATAD2 in open-access papers (continued):
Sharing a sentence is not in itself a finding about the gene and the disease.
endometrial cancer (8 papers, 2013 to 2022). Primary or metastatic malignant neoplasm involving the endometrium (mucous membrane that lines the endometrial cavity). "This study demonstrated the positive effect of ATAD2 on tumor growth in endometrial cancer and established its use as an early diagnostic marker and therapeutic target." (PMID 36479043, 2022). "The molecular mechanisms underlying the aggressive behavior of tumors with high ATAD2 is still poorly understood in endometrial cancer." (PMID 26308378, 2015). "Here we show that high ATAD2 protein expression is significantly associated with established clinical-pathological variables for aggressive endometrial cancer, also in the subset of estrogen receptor α (ERα) positive tumors." (PMID 26308378, 2015). "This strong association of expression of E2F1, E2F2 and MYBL2 with ATAD2 is found in both CAHs, primary and metastatic endometrial cancer lesions, indicating that the expression of these genes are tightly linked in all stages of endometrial cancer." (PMID 26308378, 2015). "Our data suggest that ATAD2 overexpression in human endometrial cancers is a consequence of 8q24 amplification and associated with MYC pathway activation." (PMID 23393560, 2013). "Thus, ATAD2 has the potential to be used as a molecular diagnostic marker and potential therapeutic target in the diagnosis and treatment of endometrial cancer and as an early warning sign of malignancy." (PMID 36479043, 2022). "This is contrasting the significant association between the increase in mRNA expression and increase in gene copy number, supporting that gene copy number changes are the most dominant mechanism causing the elevated expression of ATAD2 observed in endometrial cancers." (PMID 26308378, 2015). "In 2015, a study observed that the expressions of E2F transcription factor 1 (E2F1), E2F transcription factor 2 (E2F2), and MYB proto-oncogene like 2 (MYBL2) are closely associated with ATAD2, which may be related to the invasion and progression of endometrial cancer." (PMID 36479043, 2022). "In addition, our team found that high stage of Federation of Gynecology and Obstetrics (FIGO), poor pathological grading, extensive lymph node infiltration, deep myometrial infiltration, and high recurrence rate of endometrial cancer is associated with the high expression of ATAD2." (PMID 36479043, 2022). "We, therefore, conclude that the expression of ATAD2 in endometrial cancer cells promotes the expression of VEGF." (PMID 36479043, 2022). "Later, the expression of ATAD2 in human endometrial cancer cell lines as well as normal human endometrial epithelial cells was determined using protein immunoblotting." (PMID 36479043, 2022). "Basic experiments revealed that ATAD2 promotes vascular endothelial growth factor expression in endometrial cancer and affects tumor growth and angiogenesis." (PMID 36479043, 2022). "The expression of the ATAD2 protein in patient tissues was downloaded from the HPA database, which indicated that ATAD2 was highly expressed in endometrial cancer tissues." (PMID 36479043, 2022). "The results demonstrated that the overexpression of ATAD2 in the endometrial cancer cell supernatant significantly enhanced the invasive ability of HUVEC." (PMID 36479043, 2022). "ATPase family AAA structural domain-containing protein 2 (ATAD2) is an ATPase protein, which is an independent factor for poor prognosis in endometrial cancer." (PMID 36479043, 2022). "We have applied the previously validated antibody to detect ATAD2 protein expression in endometrial cancer in relation to clinico-pathological parameters." (PMID 26308378, 2015). "This is in line with previous observations regarding treatment of aggressive molecular subclasses of endometrial cancers, but needs further validation in a clinical setting, possibly alongside validation of ATAD2 as a biomarker for endometrial cancer." (PMID 26308378, 2015).
endometrial cancer (continued). "Here, we further explore expression of ATAD2 mRNA and the protein levels of ATAD2 by IHC and investigate its potential as a prognostic marker in endometrial cancer." (PMID 26308378, 2015). "We have previously identified and also recently validated ATAD2 as one of 29 genes predicting recurrence in an endometrial cancer recurrence score." (PMID 26308378, 2015). "We investigated the potential of ATAD2 as a biomarker for poor prognosis within subgroups of endometrial cancer." (PMID 26308378, 2015). "We have investigated to what extent IHC staining for ATAD2 is feasible, reflects clinical phenotype and molecular subgroups of endometrial carcinomas." (PMID 26308378, 2015). "We find that ATAD2 amplification and expression is a prognostic marker in endometrial cancer and our findings suggest that development of specific ATAD2 inhibitors is a promising approach to treatment of endometrial and other MYC driven cancers." (PMID 23393560, 2013). "We also find that progression from primary to metastatic endometrial cancer is associated with a further increase of MYC signaling and ATAD2 expression." (PMID 23393560, 2013). "ATAD2 was co-amplified to the same level as MYC in nearly all tumors (as it was among our endometrial cancers)." (PMID 23393560, 2013). "Knockdown of either ATAD2 or MYC resulted in highly correlated decreases in viability across the seven cell endometrial cancer lines (R2 = 0.70, p = 0.020)." (PMID 23393560, 2013). "Hence, in the future, we will conduct more in-depth use of basic research to explore the deeper mechanisms by which ATAD2 affects endometrial cancer angiogenesis and immune infiltration." (PMID 36479043, 2022). "All these results suggest that ATAD2 is an oncogene in endometrial cancer." (PMID 36479043, 2022). "In summary, ATAD2 promotes angiogenesis and tumor cell growth in endometrial cancer." (PMID 36479043, 2022). "Moreover, the conditioned medium of endometrial cancer cells with knocked down ATAD2 inhibited the proliferation of HUVEC to a greater extent than its control." (PMID 36479043, 2022). "Our findings suggest that ATAD2 promotes tumor growth and angiogenesis in endometrial cancer." (PMID 36479043, 2022). "In this study, Tumor IMmune Estimation Resource (TIMER) was used for ATAD2-associated pan-cancer analysis, which was followed by the analysis of ATAD2 expression and clinical relevance in Uterine Corpus Endometrial Carcinoma (UCEC) using various biochemical tools." (PMID 36479043, 2022). "Our results support ATAD2 as a prognostic marker in endometrial cancer, and also imply that ATAD2 might be a promising predictive marker for specific treatment in the future." (PMID 26308378, 2015). "We have explored the potential for clinical implementation of ATAD2 as a biomarker for aggressive endometrial cancer by investigating to what extent immunohistochemical (IHC) staining for ATAD2 is feasible, reflects clinical phenotype and molecular subgroups of endometrial carcinomas." (PMID 26308378, 2015). "We find that high expression of ATAD2 predicts poor outcome and significantly associates with markers for aggressive endometrial cancer, such as high FIGO stage and high grade, non-endometrioid type, and loss of hormone receptors AR, PR and ERα." (PMID 26308378, 2015). "Our results support that IHC staining for ATAD2 may be a clinically applicable biomarker reflecting clinical phenotype and targetable alterations in endometrial carcinomas to be further explored in controlled clinical trials." (PMID 26308378, 2015). "Taken together, our findings support that immunohistochemical staining for ATAD2 represent a clinically applicable method to measure phenotype relevant ATAD2 level in endometrial carcinomas, also with the advantage of morphologic assessment during the IHC analysis." (PMID 26308378, 2015).
endometrial cancer (continued). "We explore the role of the 8q24 amplification in endometrial cancer through integrative genomic analyses of primary and metastatic endometrial cancers with comprehensive clinical data, and identify ATAD2 as an additional target of the 8q24 amplification in these cancers." (PMID 23393560, 2013). "Our data indicate high ATAD2 expression is a marker of aggressive endometrial cancers, and suggest specific inhibitors of ATAD2 may have therapeutic utility in these and other MYC-dependent cancers." (PMID 23393560, 2013). "We demonstrate an association between high ATAD2 expression and negative outcome in endometrial cancer, using clinically well-characterized test and validation datasets." (PMID 23393560, 2013). "Our results may point to a similar regulation of ATAD2 also in endometrial cancer." (PMID 26308378, 2015). "In summary, it is an encouraging result that ATAD2 promotes VEGF expression as well as tumor growth and angiogenesis in endometrial cancer." (PMID 36479043, 2022). "Most importantly, the western blot technique verified the positive correlation between ATAD2 and VEGF expressions in endometrial cancer." (PMID 36479043, 2022). "We found that ATAD2 copy-number, ESR1 expression and E2F1 expression explained 77% of the variation in ATAD2 expression in endometrial cancer, and each of the predictor variables remained significantly associated with ATAD2 expression in the adjusted model." (PMID 23393560, 2013). "We investigated the mRNA levels of ATAD2 in a unique collection of fresh tissue from 18 precursor cancer lesions (complex atypical hyperplasias, CAHs), 141 primary endometrial cancer lesions of the endometrioid subtype and 34 of non-endometrioid subtypes, as well as 42 metastatic lesions." (PMID 26308378, 2015). "ATAD2 levels are high also in non-endometrioid endometrial cancers and metastatic lesions." (PMID 26308378, 2015). "A similar relationship between E2Fs, ATAD2 and B-MYB has not been investigated in endometrial cancer." (PMID 26308378, 2015).
esophageal squamous cell carcinoma (8 papers, 2018 to 2025). Esophageal squamous cell carcinoma (ESCC) is a type of esophageal carcinoma (EC) that can affect any part of the esophagus, but is usually located in the upper or middle third. "The overexpression of ATAD2 induces the production of the HH pathway proteins (SHH, SMO, GLI, and PTCH1) in Rb and esophageal squamous cell carcinoma cells (ESCC), which in turn promotes invasion, migration, and proliferation." (PMID 41154392, 2025). "In esophageal squamous cell carcinoma (ESCC) tissues and cell lines, ATAD2 is highly expressed, which relates to tumor TNM stage and clinicopathological progression and accelerates ESCC development through the Hedgehog (HH) signaling pathway." (PMID 36008934, 2022).
lung adenocarcinoma (8 papers, 2016 to 2026). A carcinoma that arises from the lung and is characterized by the presence of malignant glandular epithelial cells. "In lung adenocarcinoma, ATAD2 expression is associated with patient gender, smoking status, tumor stage, and lymph node metastasis and correlates with a high risk of recurrence." (PMID 37233956, 2023). "While in lung adenocarcinoma, the knockdown of ATAD2 affects glucose metabolism in cancer cells by regulating [18F] FDG uptake and lactate production through the AKT-GLUT1 / HK2 pathway." (PMID 36632213, 2023). "Variations in ATAD2 in smokers were found in non-small cell lung cancer (NSCLC) patients, and ATAD2 amplification not only regulates MYC-dependent transcription but is also a major driver of MYC-promoting lung adenocarcinoma cell proliferation." (PMID 36008934, 2022). "Furthermore, research on the gene expression of lung adenocarcinoma has shown a high correlation between ATAD2 and Myc, indicating that ATAD2 is a critical factor in Myc-regulated cell proliferation." (PMID 41154392, 2025). "This includes activating the expression of genes known to induce malignancy (ATAD2 (ATPase family AAA domain containing 2)) and genes that have been implicated in reduced survival in lung adenocarcinoma patients (GBE1 (glycogen branching enzyme), HK2 (hexokinase 2))." (PMID 36831404, 2023). "ATAD2 overexpression is closely associated with positive LUAD lymph node metastasis, poor tumor differentiation, advanced disease stage, and prognosis, and it is an individual marker of adverse prognosis after surgical resection of lung adenocarcinoma." (PMID 36008934, 2022). "RPL3, HSP90AA1, ATAD2, as well as PIAS1 and USP25, which is targeted by miR-200b, miR-200c, and miR-429 may show correlations with the sensibilization effect of HPD in lung adenocarcinoma." (PMID 30717818, 2019). "RPL3, HSP90AA1, ATAD2, and PIAS1 as well as USP25, which is targeted by miR-200b, miR-200c, and miR-429, may be the potential targets of HPD in lung adenocarcinoma." (PMID 30717818, 2019). "Recently, the overexpression of ATAD2 was found to be positively correlated with the expression of maximum standardized uptake value (SUVmax), total lesion glycolysis (TLG), glucose transporter protein 1 (GLUT1), and hexokinase 2 (HK2) in lung adenocarcinoma (LUAD) tissues." (PMID 36008934, 2022). "Therefore, ATAD2 and PIAS1 may be involved in the action mechanism of HPD in lung adenocarcinoma." (PMID 30717818, 2019).
cervical cancer (7 papers, 2017 to 2023). A primary or metastatic malignant neoplasm involving the cervix. "Several studies have previously reported significant upregulation of ATAD2 expression in solid tumors of distinct origins as well as its association with poor patients' outcome, especially in lung, breast, liver, ovarian and cervix cancers." (PMID 35049055, 2022). "Through bioinformatics analysis, ATAD2 takes an essential role in the pathogenesis of cervical cancer, and ATAD2 overexpression in cervical cancer promotes tumor cell proliferation, invasion, and metastasis." (PMID 36008934, 2022). "For example, a research in cervical cancer reported that the mRNA and protein levels of ATAD2 were elevated in cervical cancer, and the knockdown of ATAD2 impeded cell growth and metastasis." (PMID 34222668, 2021).
melanoma (7 papers, 2021 to 2026). A malignant, usually aggressive tumor composed of atypical, neoplastic melanocytes. "Combining the ATAD2 inhibitor BAY-850 with the MEK inhibitor trametinib potently suppresses melanoma growth." (PMID 41331524, 2025). "Our study identifies ATAD2 as a key driver of melanoma and provides a rationale for targeting ATAD2 in conjunction with the MAPK pathway to treat melanoma." (PMID 41331524, 2025). "We show here that the histone reader ATAD2 is overexpressed in melanoma and predicts poor prognosis, and that the MAP kinase pathway, via the transcription factor E2F1, stimulates ATAD2 expression." (PMID 41331524, 2025). "In their excellent study, ATAD2 arose as a chromatin remodeling factor required for the establishment of a progenitor signature during cell transformation, ultimately resulting in melanoma formation." (PMID 36674511, 2023). "In contrast, the addition of ATAD2 allows the cells to regain their ability to become cancerous, meaning that ATAD2 is an important factor in melanoma formation." (PMID 36632213, 2023). "More excitingly, recently it is reported that ATAD2 appears to be a necessary gene for melanoma formation in a melanoma zebrafish model, making ATAD2 a potential cancer therapeutic target." (PMID 36632213, 2023). "In melanoma, ATAD2 interacts with SOX10 and c-Myc, serving as a crucial gene." (PMID 41158756, 2026). "Importantly, ATAD2 is essential for tumorigenesis in melanoma 14, and overexpression of ATAD2 can facilitate the proliferation of tumor cells and impede apoptosis in a variety of malignancies." (PMID 36632213, 2023). "For instance, a recent study revealed that ATAD2 could promote the formation of melanoma phenotypes through chromatin remodeling." (PMID 36632213, 2023). "Furthermore, ATAD2 was recently reported as an oncogenic competence factor required for melanoma initiation in melanocytes." (PMID 36674511, 2023). "As a first step in order to understand if the selected E2F target genes could function as predictor markers of CDK4/6 inhibition resistance, we compared the expression profiles of E2F1, CDC6, DHFR, H2AFZ, MCM2, and ATAD2 among the four canine melanoma cell lines." (PMID 34485433, 2021). "Mechanistically, we show that ATAD2 inhibition activates both distinct and common tumor-suppressive pathways in BRAF and NRAS mutant melanoma." (PMID 41331524, 2025). "Genetic or pharmacological inhibition of ATAD2 suppresses the growth and metastasis of BRAF and NRAS mutant melanoma." (PMID 41331524, 2025). "In a novel human pluripotent stem cell-based cancer model, ATAD2 is required for the response to the oncogene BRAF and tumor initiation in melanoma." (PMID 36008934, 2022). "ATAD2 is a key chromatin modifier that forms a complex with SOX10, enabling the expression of downstream oncogenic programs and promoting the melanoma phenotype." (PMID 36008934, 2022). "Together, high ATAD2 levels supported the re-expression of a progenitor signature and may thus help mutant BRAF to initiate melanomas." (PMID 34930891, 2021).
lymph node metastasis (6 papers, 2015 to 2023). "We then analyzed the correlation between ATAD2 expression and clinicopathological features, and ATAD2 expression was found to be significantly associated with lymph node metastasis (P = 0.002) and advanced stage (P = 0.028)." (PMID 33757572, 2021). "We found that elevated ATAD2 expression was significantly associated with lymph node metastasis, advanced clinical stage as well as poor survival of ESCC patients." (PMID 33757572, 2021). "As ATAD2 was significantly associated with lymph node metastasis in ESCC patients and promoted cell migration and invasion as well as lung metastasis in mice, we further devoted to find out the underline pro-metastatic mechanism of ATAD2." (PMID 33757572, 2021). "In this study, we found that ATAD2 expression was significantly associated with lymph node metastasis and advanced clinical stage, and revealed the prognostic role of ATAD2 in a relatively large cohort of ESCC patients." (PMID 33757572, 2021). "High level of ATAD2 expression was correlated with lymph node metastasis and advanced clinical stage and predicted poor overall survival in ESCC patients, which indicated an oncogenic role of ATAD2 in ESCC." (PMID 33757572, 2021). "ATAD2 is also positively correlated with UCEC stage, histological grade, depth of myometrial invasion, lymph node metastasis, lymphatic space involvement, and recurrence, and can be used as an independent poor prognostic indicator." (PMID 36008934, 2022). "The results indicated that high expression of ATAD2 in CRC tissues is closely correlated with tumor size (P < 0.001), serum CEA level (P = 0.012), lymph node metastasis (P = 0.018), liver metastasis (P = 0.025), and clinical stage (P = 0.004)." (PMID 26697062, 2015). "Our results revealed similar phenomenon that ATAD2 has positive correlation with serum CEA level, lymph node metastasis, distant metastasis, and clinical stage in CRC." (PMID 26697062, 2015). "The results showed that high expression of ATAD2 was significantly correlated with tumor size (P < 0.001), serum CEA (P = 0.012), lymph node metastasis (P = 0.018), liver metastasis (P = 0.025), and clinical stage (P = 0.004)." (PMID 26697062, 2015).